CD47 (CD47 molecule)
Diseases named in the same sentence as CD47 in open-access papers (continued):
Sharing a sentence is not in itself a finding about the gene and the disease.
tumor (continued). "Supplementation with Bifidobacterium can activate STING signal through its accumulation in local tumor microenvironment, thereby promoting antigen presentation of DC cells and enhancing the anti-tumor effect of CD47 inhibitor." (PMID 36465375, 2022). "ADCP and ADCC are negatively regulated by interactions between CD47 on tumor cells and signal regulatory protein alpha (SIRPα) on effector cells." (PMID 36052078, 2022). "CD47, a receptor overexpressed on tumor cells, recognized the signal-regulatory protein α (SIRPα) on macrophages and protected the tumor cells from phagocytosis." (PMID 36311702, 2022). "Blocking the “don’t-eat-me” signal on tumor cells with anti-CD47 antibodies enhances the therapeutic efficacy of olaparib in a mouse model." (PMID 36223740, 2022). "In clinical settings, even if complete responses (CRs) were reported in some anti-CD47 trials, CRs were mostly below 50% and only affecting a sub-population of tumor patients." (PMID 35664753, 2022). "The propensity of tumor cell CD47 to bind to signal regulatory protein alpha (SIRPα) on the macrophage, thus creating a checkpoint, spares the tumor cell from phagocytosis." (PMID 36276103, 2022). "CD47 cross-dressing also suggests a previously unidentified mechanism for tumor-induced immunosuppression." (PMID 36454036, 2022). "All the three prophagocytic receptors can be exploited to enhance anti-tumor response during CD47-SIRPα blockade." (PMID 36081498, 2022). "A high CD47 expression on tumor or CTC surfaces indicates a strong migration and invasion and renders them protected from phagocytosis from immune cells, such as T cells, NK cells and macrophages." (PMID 35406441, 2022). "Another checkpoint molecule on tumor cells is CD47, which binds to signal-regulatory protein-α (SIRP-α) on monocytes, macrophages, and neutrophils." (PMID 36436127, 2022). "Living (tumor) cells, on the other hand, prevent phagocytotic clearance through the sustained presentation of “don’t eat me” surface signals, such as CD47." (PMID 34665291, 2022). "The possible reason is that the density of SIRPα on the surface of exosomes was high, allowing aggregation into active clusters after binding to CD47 overexpressed on the surface of tumor cells and thereby promoting signal transduction." (PMID 35566065, 2022). "IBI322 treatment outperformed treatment with a combination of PD‐L1 + CD47 mAb in controlling tumour growth of PDL1+CD47+ Raji cells after injection with human PBMC." (PMID 35908284, 2022). "HIF-1α is also involved in the upregulation of the macrophage immune checkpoint CD47 on the surface of tumor cells inducing tumor cell escape from phagocytosis." (PMID 35910347, 2022). "While blocking endogenic CD47-SIRPα signals between tumor cells and phagocytes, SIRPαFc would promote antitumor innate immunity and tumor antigen presenting to activate adaptive immunity." (PMID 35422796, 2022). "IBI322 selectively binds CD47+PD-L1+ tumor cells, effectively inhibits CD47/SIRPα signaling, and instigates intense phagocytosis of CD47+PD-L1+ tumor cells by macrophages in vitro." (PMID 35978372, 2022). "Our results revealed that, compared with that in normal tissues, CD47 was upregulated in HCC tumor tissues (p < 0.001)." (PMID 35559014, 2022). "CD47 is a transmembrane protein with a well-described role as a “don’t eat me” signal due to its binding to signal regulatory protein α (SIRPα) on myeloid cells and high CD47 expression on tumor cells is thought to protect tumor cells from immune responses." (PMID 35720306, 2022). "Conversely, we found remarkably lower tumor cell PD-L1 expression than CD47 expression with an overall positivity rate of 9.6% (10/102)." (PMID 36399951, 2022). "Several investigations have exhibited the potential role of CD47 blockade in producing anti-tumor effects." (PMID 35978372, 2022). "ICD inducers can promote the expression of pro-phagocytic signals in tumor cells, while anti-CD47 treatment can block the “don’t eat me” signal." (PMID 36230638, 2022).
tumor (continued). "Here, we show that CD47 ablation is insufficient on its own to affect tumor progression in a poorly immunogenic, metastatic model that is widely used as a pre-clinical model." (PMID 35454837, 2022). "In BALB/C mice, murine SIRPα‐Fc‐CD40L increased tumour rejection rates and long‐term immunity compared to treatment with CD47 mAb, CD40 agonist antibody, or the combination of these." (PMID 35908284, 2022). "As a crucial phagocytosis signaling pathway between macrophages and tumors, CD47/SIRPα axis is likely to be an effective target for tumor immunotherapy." (PMID 35410993, 2022). "CD47 is a marker of self-recognition present on tumour and normal tissue that precipitates an anti-phagocytic signal upon binding to the signal regulatory protein alpha (SIRPα) transmembrane protein on the surface of macrophages." (PMID 35954487, 2022). "As potential tumor vaccine vectors, oncolytic viruses can be engineered to express anti-CD47 antibodies to induce potentiated tumor killing." (PMID 35837100, 2022). "CD47, a 'marker-of-self' protein that is broadly overexpressed across tumor cells, is also emerging as a novel macrophage immune checkpoint for cancer immunotherapy." (PMID 35547750, 2022). "For example, the binding of CD47 to signal regulatory protein α (SIRPα) on macrophages reduces their anti-tumor response, which can be restored by blocking this interaction." (PMID 35865547, 2022). "We conducted a retrospective study investigating the expression of the CD47 molecule in both tumor cells and tumor-infiltrating immune cells (TIIC) in the center and periphery of primary tumors from 43 patients with SGC with 5 different histological subtypes." (PMID 36171566, 2022). "The fibrinogen solution containing anti-CD47 antibody-loaded CaCO3 nanoparticles and thrombin solution can be quickly sprayed and mixed within the tumour resection cavity after surgery to form the gel in situ." (PMID 36463199, 2022). "In tumor microenvironment, CD47 impairs the recruitment of NK cells, whereas treatment with anti-CD47 antibody increases NK cells killing against tumor cells by enhancing expression of granzyme B and IFN-γ." (PMID 36081498, 2022). "The hybrids exhibited sustained blood circulation and improved macrophage-mediated phagocytosis of tumor cells by blocking CD47 signaling." (PMID 36051588, 2022). "Tumor cells express don't eat me signal CD47 in a glioblastoma multiforme model, to prevent being cleared by microglial phagocytosis." (PMID 35142399, 2022). "GPC3/CD47, a bispecific antibody targeting GPC3 and CD47, was effective in preventing tumor growth through recognition of both antigens." (PMID 35251989, 2022). "The CD47–SIRPα axis is the most common “don’t eat me” axis, whose neutralization by anti-CD47 or anti-SIRPα antibodies can enhance phagocytic clearance of cancer cells in many preclinical tumor models." (PMID 35158779, 2022). "in the tumor, which reversed the resistance of anti-CD47 immunotherapy in a colon cancer mouse model." (PMID 36429112, 2022). "Transcriptional CD47 super enhancers were found in tumor cells with a high level of CD47 expression." (PMID 35865547, 2022). "CD47 blockade using Hu5F9-G4, a humanized IgG4 antibody binding CD47, in combination with Rituximab, is believed to restore the phagocytosis of tumor cells initiated by Rituximab." (PMID 35326604, 2022). "Macrophages, the innate defense of the immune system, are limited in their phagocytosis by CD47 anti-phagocytic signaling expressed on the surface of tumor cells." (PMID 35832081, 2022). "Blocking the CD47-SIRPα axis therefore results in enhanced integrin activation, subsequently stimulating trogoptosis of antibody-opsonized tumor cells." (PMID 35884427, 2022). "Tumor cells take advantage of this system via overexpression of CD47, providing a unique immune escape mechanism that has garnered considerable interest." (PMID 36031601, 2022).
tumor (continued). "In vivo studies showed that this strategy can locally reverse immunosuppression, synergistically block CD47-related immune escape, and effectively prevent tumor recurrence and metastasis." (PMID 35664074, 2022). "CD47 has also become a focus of research in cancer, as tumor cells express CD47 to escape macrophage-mediated phagocytosis." (PMID 36428745, 2022). "In two studies, antisense suppression of CD47 using a morpholino oligonucleotide combined with RT (10 Gy) in mice, resulted in less tumor volume compared to the control group." (PMID 36018888, 2022). "Cancer cell membranes retain a large number of surface antigens and tumor adhesion molecules CD47, which can be used to camouflage the metal complex and give it tumor homing ability and high biocompatibility." (PMID 36064356, 2022). "These dose-limiting toxicities demonstrate the need to highlight the mechanisms of anti–CD47-SIRPα therapy effects on non-tumor CD47-bearing cells." (PMID 35795660, 2022). "We observed that the highest proportions of CD47+ tumor cells were in the tumor periphery of AdCaNOS." (PMID 36171566, 2022). "For each histological subtype, the proportion of CD47+ tumor cells in the tumor center was comparable to the proportion of CD47+ TIICs." (PMID 36171566, 2022). "Studies in immunocompetent animal models suggest that adaptive immune responses subsequent to CD47/SIRPα blockade are significantly involved in tumor growth control." (PMID 35538512, 2022). "They believed that determining CD47 expression levels in bone marrow or peripheral blood contributed to predict the number of circulating tumor cells that escaped from the immune system, which is indicative of the presence of micrometastases." (PMID 35860564, 2022). "Here, macrophage‐mediated phagocytosis did not outperform single RTX treatment in vitro, but the bsAb did delay tumour growth of Raji cells significantly better than CD47 or CD20 single block in NOD/Shi‐scid/IL‐2Rγnull(NOG) mice." (PMID 35908284, 2022). "reveal data suggesting that T cells are required for tumor regression and mediate most of the anti-tumor effects of the CD47 blockade." (PMID 36081498, 2022). "In terms of tumor ligand expression, compared with the Saline group, the protein levels of CD47, CD24, and PD-L1 in the CON group were significantly increased (P<0.05)." (PMID 36186906, 2022). "Critically, CD47 is overexpressed in a number of tumours, and CD47 blockade has been identified as an attractive immunotherapy target." (PMID 35261190, 2022). "Since the discovery of the first tumor phagocytosis-related checkpoint, namely the CD47/SIRPα axis, in the late 2000s, other tumor phagocytosis-related checkpoints have been identified: the PD-1/PD-L1 axis, MHC-I/LILRB1 axis, and CD24/SIGLEC-10 axis." (PMID 35978372, 2022). "The programmed cell death 1 ligand 1 (PD-L1) on the tumor cell membrane can inhibit the immune function of T cells, and the CD47 protein can prevent the phagocytosis of tumor cells by macrophages and dendritic cells." (PMID 35664731, 2022). "Our results with a standard pre-clinical cancer model contrast with many early reports that anti-CD47 monotherapy can suppress tumor growth in various mouse models (often xenogeneic in immunodeficient mice)." (PMID 35454837, 2022). "CD47 Inhibition in combination with RT can protect normal cells against RT while increasing the sensitivity of tumor cells to RT and impairing tumor progression." (PMID 36018888, 2022). "SIRPα-exosomes inhibited tumor growth by binding to and suppressing the function of CD47, a “don’t eat me” signal overexpressed on cancer cells, therefore promoting the engulfment of tumor cells by macrophages." (PMID 35054611, 2022). "In low-grade tumors, significantly higher expression of CD47 was observed in TIICs in the periphery of the tumor as compared to the center of the tumor." (PMID 36171566, 2022).
tumor (continued). "IgG-based BsAbs have been generated based on this theory to block CD47 and specific tumor biomarkers or other immune cell biomarkers." (PMID 35978372, 2022). "The CD47/SIRPα axis is the predominant mechanism by which tumor cells resist macrophage phagocytosis." (PMID 35965509, 2022). "Thrombospondin-1 (TSP) is a secreted glycoprotein that is also a ligand of CD47; it is a known gatekeeper of tumor progression that sometimes has opposite effects." (PMID 36429020, 2022). "Given the anti-tumor mechanisms and AEs of CD47/SIRPα blockades found in hematological malignancies’ treatment research, several points should be considered during drug design and development: 1) Can CD47 antibodies interact with RBCs?" (PMID 35978372, 2022). "The exosome delivery system improved the survival rate in LLC tumor‐bearing mice compared to co‐administration of cisplatin and CD47 blocking antibodies." (PMID 36054073, 2022). "CD47 is overexpressed in a variety of tumors, and is involved in tumor invasion, metastasis, and the inhibition of phagocytosis by interacting with SIRPα-expressing phagocytes." (PMID 35053602, 2022). "Studies have shown that blocking the CD47/SIRPα signaling pathway between tumor cells and phagocytes can increase the phagocytosis of tumor cells by innate immune cells, thereby enhancing the antitumor immune response." (PMID 35566065, 2022). "Blockade of the CD47/SIRPα interaction can inhibit tumor growth by inhibiting the suppressive effects of SIRPα and promoting macrophage activity." (PMID 36080360, 2022). "So far, multiple phase I clinical trials focusing on CD47 suppression have been initiated and have shown limited results, largely due to toxicity concerns due to CD47’s ubiquitous expression in many non-tumour organ systems." (PMID 36497148, 2022). "It has become increasingly evident that the CD47-SIRPα pathway plays a critical role in containing anti-tumor immune responses." (PMID 36454036, 2022). "Inhibition of CD47-SIRPα by the decreased expression of CD47 on tumor cells further enhanced anti-tumor effects of neutrophils." (PMID 35884427, 2022). "Tumor cells express both PD-L1 and CD47, whereas most normal cells have limited or undetectable expression of PD-L1." (PMID 35978372, 2022). "A previous study also demonstrated that inhibition of glucose-regulated protein 78 (GRP78), a member of the HSP70 family, downregulated CD47 expression in tumor cells." (PMID 35678681, 2022). "Using the BNCT effect of DOX-CB combined with the improved phagocytosis of CD47-blocked tumor cells and tumor stem cells, the study increased anti-tumor effectiveness, reduced the recurrence rate, and prolonged the survival time." (PMID 35246144, 2022). "Studies of human tumor samples found that many tumor cell types highly express CD47, and that such expression is related to poor prognosis in cancer patients." (PMID 35454882, 2022). "Phagocytosis modulation via the CD47 blockade alone proved to have limited anti-tumor effects, with only a slight increase of phagocytosis in human GBM cells." (PMID 35054787, 2022). "Here, in this study, we used a replication-selective oncolytic adenovirus to intratumorally deliver a CD47-targeting nanobody for reducing off-tumor toxicity and enhancing therapeutic efficacy." (PMID 35837100, 2022). "For example, tumour cell CD47 and CD24 engage cognate receptors on TAMs, signal regulatory protein-α (SIRPα) and sialic acid-binding Ig-like lectin 10 (Siglec-10), respectively, to trigger signalling cascades which inhibit macrophage phagocytosis." (PMID 35020853, 2022). "CD47, an inhibitory ligand expressed on tumor cells, often interacts with SIRPα on macrophages to transmit a “don’t eat me” signal to escape the phagocytosis by macrophages." (PMID 35410993, 2022).
tumor (continued). "To date, ITIM bearing sialic acid-binding immunoglobulin-like lectins (Siglecs) expressed on myeloid cells have been discovered to bind to tumor cell ligands and inhibit immune responses in a manner similar to the CD47-SIRPα interaction." (PMID 35865547, 2022). "Anti-CD47 antibody blockade exhibits inhibitory effects on tumor growth and tumor metastasis in murine ovarian cancer model." (PMID 35646915, 2022). "Anti-Tyrp1 therapy of mice bearing CD47-deleted metastases nonetheless resulted in lower overall tumor burden even though mice succumbed with similar clinical symptoms as untreated controls." (PMID 35454837, 2022). "Targeting the CD47/SIRPα axis has become a promising strategy to promote tumor elimination through innate immunity." (PMID 35418166, 2022). "The FAO-inducible CD47 promoter activity further supports a dynamic CD47 level in an irradiated tumor microenvironment." (PMID 35314680, 2022). "Previous research has shown increased VEGF-A expression in tumours from CD47 blockade in tumour stromal cells." (PMID 35694254, 2022). "Regardless, complete CD47 disruption combined with a tumor-opsonizing antibody significantly suppresses metastatic-type tumor growth and prolongs survival." (PMID 35454837, 2022). "At the same time, SIRPα-expressing ferritin induced massive phagocytosis of tumor cells by macrophages by blocking the SIRPα/CD47 pathway." (PMID 35566065, 2022). "Based on these results, treatment with Bev (10 mg/kg) + anti-CD47 (20 mg/kg) reduced the tumour volume by 84.64 ± 5.23%." (PMID 35694254, 2022). "Here, we found that macrophage-secreted IL-18 upregulated LAT2 in tumor cells, which enhanced the uptake of Gln and Leu to upregulate CD47 for inhibition of macrophage phagocytosis." (PMID 36274066, 2022). "Blocking the CD47 receptor by soluble SIRP-α, (a thrombospondin-1 family member, CD47 decoy receptor) restored the macrophage phagocytosis of Sezary cells, resulting in tumor load reduction in peripheral blood." (PMID 36059451, 2022). "In vitro and in vivo studies showed that NI1701 more potently killed tumor cells than did anti-CD47 and anti-CD19 antibodies alone, or in combination." (PMID 35418166, 2022). "Unlike the adaptive immune checkpoint PD-L1 who sends to the adaptive immune system a “don’t find me” signal, cluster of differentiation 47 (CD47) sends a “don’t eat me” signal to the innate immune system that blocks macrophages from attacking the tumor." (PMID 35428347, 2022). "Correspondingly, growth of persistently implanted syngeneic B16 tumors was faster in Cd47−/− mice, which also correlated with the decreasing number and effector phenotypes of tumor-infiltrating CD8+ T cells." (PMID 36105746, 2022). "D4–2, a macrocyclic peptide targeted to mouse SIRPα was designed to inhibit the interaction between CD47 and SIRPα and promote macrophage-mediated phagocytosis of tumor cells when combined with rituximab." (PMID 35418166, 2022). "Recent work has demonstrated the great potential of synergistic anti-tumor effects through the dual-blocking of the PD-1/PD-L1 and CD47/SIRP-α immune checkpoint pathways." (PMID 36009390, 2022). "On intravenous administration, they specifically recognize CD47 on the surface of tumor cells by aCD47." (PMID 35183252, 2022). "The potent CD47 mAb-induced PMN cytotoxicity was not limited to primary T cells as we observed similar cytotoxicity with Raji tumor cells (Raji) as targets." (PMID 35795660, 2022). "Following the co-internalization of CXCR4 and CD47 in tumor cells, macrophages phagocytose them and cross-present their antigens to the adaptive immune system, leading to tumor rejection in a fraction of mice." (PMID 35565443, 2022). "Quite a few anti-CD47 and anti-SIRPα antibodies are already undergoing clinical trials for tumor treatment." (PMID 35746616, 2022).